JAK2 (Janus kinase 2)
Diseases named in the same sentence as JAK2 in open-access papers (continued):
Sharing a sentence is not in itself a finding about the gene and the disease.
tumor (continued). "Many small-molecule inhibitors of JAKs, or STAT TFs, especially JAK2 and STAT3, have been assessed for their anti-tumor activity in GBM." (PMID 37947625, 2023). "Specifically, we found that upregulation of miR-181b in HB cells promotes tumor metastasis by inhibiting the expression of SOCS2, which leads to activation of JAK2/STAT5 signaling and subsequent promotion of EMT related to invasion." (PMID 37955014, 2023). "In MG-63 xenograft mice, curcumin decreases tumor size and p-JAK2 and STAT3 expressions, further validating tumor growth suppression through the JAK2/STAT3 pathway." (PMID 36923933, 2023). "This constitutively active JAK2 form, that hyperactivates the STAT3 phosphorylation, leads to upregulation of PD-L1 and to the immune escape of neoplasms." (PMID 36672229, 2023). "In the tumor microenvironment, continuous stimulation with IL-6 can activate JAK2, resulting in STAT3 phosphorylation and thereby promoting tumor growth, drug resistance, and metastasis." (PMID 37817809, 2023). "Eckol, a novel natural phizolian derived from marine brown algae, has been shown to downregulate EGFR, p-EGFR, JAK2, and STAT3 expression in tumor cells, indicating pro-apoptotic and anti-proliferative activities." (PMID 37859983, 2023). "The recent advances in CAF-based therapy are based on targeting the markers to ablate CAFs, restoring activated CAFs to quiescent ones, and blocking the signalling between CAFs and tumour cells, such as JAK1/JAK2 and CXCL12/CXCR." (PMID 36980527, 2023). "PRL-3 promoted tumor progression through various pathways, such as PI3K-AKT-ERK, NFκB and Jak2-STATs pathways 21, 24-26." (PMID 37670977, 2023). "For example, CAF-secreted IL-6 enhances tumor cells’ epithelial–mesenchymal transition (EMT) via the activation of the Janus kinase 2/signal transducers and activators of the transcription 3 (JAK2/STAT3) pathway in GC." (PMID 37173977, 2023). "In the protein level, the gene expression of HSP90AA1, NFKB2, PTK2 was upregulated in tumor tissues, and CLU, JAK2, MAP3K5, and S100B were downregulated in the normal tissues." (PMID 36323529, 2023). "Activation of the IL-6/JAK2/STAT3 signaling pathway is involved in the development and progression of tumors and contributes to the formation of the tumor inflammatory microenvironment." (PMID 37817809, 2023). "Il-6 via the membrane receptor activates non-receptor tyrosine kinases including JAK2, which induce the JAK2/STAT3 cascade for angiogenesis and tumor enlargement because of regulating progression of the cell cycle." (PMID 37373969, 2023). "Activation of different signaling cascades such as JAK2/STAT3, NF-κB, PI3K/AKT/mTOR, and Wnt/β-catenin pathways through the tumor microenvironment leads to upregulation of antiapoptotic proteins." (PMID 36986514, 2023). "Here, we will review the current evidence on the biological factors, such as additional mutations and chronic inflammation, which influence clonal expansion and may determine why some JAK2-mutated individuals will progress to an overt neoplasm during their lifetime while others will not." (PMID 37628880, 2023). "The JAK2 signaling transduction pathway phosphorylates STAT3, triggering the activation of pathways related to the production of chemokines released in the tumor microenvironment, promoting the attraction of macrophages." (PMID 37628945, 2023). "We evaluated tumor characteristics by PRLR, pSTAT5, and JAK2 expression among premenopausal and postmenopausal women." (PMID 36882838, 2023). "JAK2/STAT3 signaling pathway plays a key role in cell proliferation, division, migration, tumor formation and immune cell maintenance." (PMID 37465679, 2023).
tumor (continued). "Negative regulation of the IL-6/JAK2/STAT3 signaling pathway enhanced apoptosis and autophagy in tumor cells, thereby improving the therapeutic effect on GBM." (PMID 37057281, 2023). "The JAK2/STAT3 axis is activated in human GC tissues, and JAK2/STAT3 signaling activation exerts a role in tumor growth and metastasis." (PMID 36814203, 2023). "The JAK2/STAT5 signaling pathway is activated in various types of tumors and is considered a promising drug target for tumor treatment." (PMID 38071211, 2023). "JAK1/JAK2 inhibitor (JAKi) has been applied to inhibit expression of TCIR ligands and improved ICBT response in preclinical tumour models." (PMID 37503572, 2023). "On the other hand, neutrophils/chemerin induced EMT of OSCC also through the JAK2/STAT3 pathway and further promoted tumor migration and invasion via EMT." (PMID 35155249, 2022). "Subsequently, the data of western blotting showed that the protein levels of phosphorylated-JAK2, N-cadherin and VEGFA were reduced in tumor tissues exposed to oridonin, while E-cadherin protein level was elevated." (PMID 35813296, 2022). "Through regulating the JAK2/STAT3/FOXM1 axis, in vivo tumor xenograft assays further demonstrated that knockdown of AGK inhibited tumor development and decreased resistance to paclitaxel." (PMID 36313702, 2022). "Treatment of Jak2 inhibitor AZD1480 suppresses PCa xenograft tumor development, and prolongs survival time of tumor-bearing mice as compared with vehicle or docetaxel-treated groups." (PMID 35335873, 2022). "The miR-375 gene is important for insulin secretion and glycogen synthase and acts as a tumor suppressor by downregulating numerous oncogenes, e.g. PDK1, JAK2, IGF1R, AEG-1, and suppressing the PI3K/Akt pathway." (PMID 35284957, 2022). "The JAK2-STAT pathway, which is vital for communicating chemical signals from the outside of cells to the nucleus, is involved in cell division, cell death, tumor formation, and immunity." (PMID 35162937, 2022). "The IL-6/JAK2/STAT3 pathway and CXCL12/CXCR4 interactions between tumor cells and CAFs were enriched." (PMID 35784460, 2022). "It was revealed that the binding of GZMA to the LDPRSFLL motif at the N-terminus of F2R promotes apoptosis via JAK2/STAT1 signaling, which in synergy with the PD-1 mAb therapy led to tumor suppression in both mouse model and HCC patients." (PMID 35256589, 2022). "FGFs activate MAPK-ERK, JAK2/STAT3 and PI3K/AKT signalling pathways, which has been identified as key mediators in tumour progression promotion." (PMID 35864158, 2022). "A large number of studies have shown that IL-6/JAK2/STAT3 signaling pathway is abnormally highly activated in many types of cancer and strongly inhibits anti-tumor immune response." (PMID 36591515, 2022). "To directly confirm this finding, we analyzed phosphorylation of JAK1 and JAK2 (p-JAK1 and p-JAK2) by Western blot (WB) in cells cultured under normoxia (21% O2) and hypoxia (1% O2, mimicking hypoxic tumor microenvironment [TME])." (PMID 36008408, 2022). "In our study, the knockdown of JAK2 and ITGA5, including fibronectin (upstream factors involved in the initial tumor spheroid formation) mediated significant reductions in the levels of LMO2 and LDB1." (PMID 36359204, 2022). "We suggest that JAK2 increases GMP expansion through its inhibitory effect on NOTCH via the MAPK pathway and ITCH and so predict a tumour suppressor role for NOTCH in the GMP cell population." (PMID 36192425, 2022). "In this study, we discovered that that knockdown of Chemerin only partially inhibited JAK2 or STAT3 phosphorylation, indicating that Chemerin partially contributed to the tumor-promoting effect of neutrophils on OSCC cells." (PMID 35155249, 2022). "Previous studies have reported that JAK2/STAT3 pathway regulated the expression of CCL20 and tumor angiogenesis." (PMID 35642002, 2022).
tumor (continued). "The volume and weight of the transplanted tumor was measured, and the expression of p-JAK2 and p-STAT3 and cell apoptosis in the xenograft tumor tissues were detected." (PMID 35909161, 2022). "After blocking IL-6/JAK2/STAT3 pathway and inhibiting DNMT1, the proliferation of lung CSCs, the formation of spheres and the ability to initiate tumor growth decrease." (PMID 36591515, 2022). "The activation of REG3A will enhance JAK2/STAT3 pathway, amplify the carcinogenic effect of IL-6/JAK2/STAT3, and ultimately leads to excessive PC cell proliferation in vitro and in vivo and tumor formation." (PMID 36591515, 2022). "To examine the significance of upstream genes involved in STAT3 activation regulating properties of tumor spheroids, we knocked down FN1, ITGA5, JAK1, JAK2, LDB1, and LMO2 from the cells." (PMID 36359204, 2022). "JH2 maintains the tyrosine kinase activity of JAK2 at a low basal level and maintains normal cellular activity; accordingly, it also indicated that JH2 has a tumor suppressor function." (PMID 35162937, 2022). "At the molecular level, CCL21/CCR7 can promote lymphatic metastasis of tumours via activating the ERK1/2 22 and JAK2/STAT3 signalling pathways." (PMID 35280672, 2022). "Our data support the tumor-suppressor function of SOCS3 and highlights the role of SOCS3/JAK2/STAT3 axis in PCa progression." (PMID 35818076, 2022). "In line with the fact that Ruxo is a well-established JAK1/2 inhibitor, we observed the expected suppression of p-JAK2 and p-STAT3 in tumor (CD45−) cells by Ruxo." (PMID 36008408, 2022). "The JAK2/STAT3 signaling pathway is of significance in the regulation of oxidative stress, cellular autophagy, inflammatory response, and tumor progression." (PMID 36104717, 2022). "In yet another Panc-1 study in which CuB (at 0.5–1.0 mg/kg) reduced tumor volume when cells in Matrigel were grafted into nude mice, alterations in JAK-STAT signaling (i.e., reduced levels of p-STAT3 and p-JAK2) were also noted." (PMID 36355554, 2022). "Mechanistically, through comprehensive biochemical screening and tumor samples profiling, we identified UCHL3 as a crucial deubiquitinase that binds explicitly to JAK2-phosphorylated BRD4 to maintain its stabilization." (PMID 34290255, 2021). "JAK2/STAT3 signaling pathway plays a critical role in the occurrence and development of tumor cells." (PMID 34165442, 2021). "Here we report that nicotine enhances ESCC cancer malignancy and tumor-initiating capacity by interacting with cholinergic receptor nicotinic alpha 7 subunit (CHRNA7) and subsequently activating the JAK2/STAT3 signaling pathway." (PMID 33603170, 2021). "Meanwhile, IHC staining was performed to confirm that the phosphorylation levels of MEK1/2, ERK1/2, JAK2, STAT3, PI3K, and Akt in tumor tissues of mice inoculated with A549, BxPC-3, and SKOV3 cells, respectively." (PMID 34642304, 2021). "JAK2/STAT3, a critical signaling pathway in tumorigenesis, is mediated through EGFR signaling; STAT3 can act as a transcription factor for tumor progression." (PMID 33805840, 2021). "Herein, we provide the first evidence that Niclocide is an inhibitor of tumor growth and metastasis in PTC, complementing its biological function via influencing the dynamic properties of regulating JAK2/STAT3 signaling network." (PMID 34404767, 2021). "The network consists of a system of ordinary differential equations (ODEs) involving eight variables: concentrations of STAT1, STAT3, Bcl-2, BAX, IFN-β, JAK2 and DDP and tumour volume." (PMID 34631119, 2021).
tumor (continued). "Oxymatrine plays a significant role in regulating cell proliferation and survival in tumor cells by inhibiting the activation of JAK1 and JAK2, thereby inhibiting the phosphorylation and nuclear translocation of STAT5." (PMID 34809653, 2021). "Herein, we provide the first evidence that ANXA1 is a positive regulator of tumor growth and metastasis in PTC, complementing its biological function via influencing the dynamic properties of EMT and regulating IL-6/JAK2/STAT3 signaling network." (PMID 33531975, 2021). "In non‐small cell lung cancer, mesenchymal stem cells were shown to promote the formation of cancer stem cells through the IL6/JAK2/STAT3 pathway and to promote tumor invasion and migration." (PMID 33788424, 2021). "Collectively, our western blot results revealed that miR-195-5p upregulation reduced the protein expression levels of p-p38, p-JAK2 and p-STAT1 in PTC cells and tumor xenografts, CircRNA NRIP1 overexpression reversed those effects." (PMID 34689819, 2021). "In tumor B cell lines, Fyn interacts with the activated forms of TYK2 and JAK2 in response to IFN-α or IFN-γ stimulation respectively." (PMID 33668421, 2021). "Subsequently, total RNA and protein of nude mice tumor tissues were extracted, and qPCR and western blot experiments were carried out to measure the level of lncRNA MALAT1 and JAK2 protein." (PMID 34987594, 2021). "JAK2/STAT3/VEGF signalling is activated during angiogenesis in vivo, and tumour suppressor gene, PARK2, was shown to inhibit tumour growth and angiogenesis in vivo by downregulating the JAK2/STAT3/VEGF pathway." (PMID 33382511, 2021). "Further, we found emerging of new JAK2 and ATM alterations in patient B8 at the second time point, indicating possible evolving tumor clonal growth during disease progression." (PMID 34336686, 2021). "Thus, activation of the JAK2-STAT signaling pathway may promote tumor growth in HL." (PMID 34925435, 2021). "It was revealed that in GC tumor tissues and GC cells, in contrast with the Vector group, CALM2 overexpression greatly facilitated JAK2 and STAT3 phosphorylation and elevated the protein expressions of HIF-1 and VEGFA." (PMID 34604066, 2021). "For instance, to facilitate tumorigenesis, hsa_circ_101280 serves as a sponge for miR-375 and upregulates JAK2 expression, thereby promoting the proliferation of HCC cells as well as suppressing tumor cell apoptosis." (PMID 34294754, 2021). "JAK2/STAT3 pathway, which is one of the best understood signal transduction cascades, plays a key role in tumor immune microenvironment." (PMID 34881181, 2021). "Anlotinib targets JAK2/STAT3/VEGFR signaling, and the inhibition of angiogenesis halts tumor proliferation and promotes apoptosis." (PMID 34955687, 2021). "A JAK2/STAT3 signaling pathway has been previously found activated abnormally in varieties of tumor tissues, which exerts great impact on tumor progression." (PMID 34663387, 2021). "Previous studies confirmed that AKR1C1 promotes tumor metastasis via phosphorylating STAT3 and its upstream kinase JAK2 (JAK2/STAT3 pathway)." (PMID 34938341, 2021). "Secondary alterations affecting cytokine signalling occurred in 37% iAMP21 of tumours (QBinomial = 2.2 × 10−3) involving IL7R, JAK2 or CRLF2 (including 3/5 cases of P2RY8-CRLF2 translocation)." (PMID 34753926, 2021). "Combination of a JAK2 inhibitor with chemotherapy inhibited this SASP pro‐inflammatory network, increasing infiltration of T cells and decreasing tumour burden." (PMID 34137158, 2021). "Recent research has shown that the JAK2/STAT3 pathway plays a key role in tumorigenesis and progression of a variety of tumor types." (PMID 33788424, 2021). "miR-21, a key regulator of apoptosis and tumor progression, can be overexpressed in tumor-stimulated macrophages and downregulate STAT1 and Janus kinase 2 (JAK2)." (PMID 35116035, 2021). "RPS6-KD reduced p-JAK2 and p-STAT3 and suppressed the tumor sphere formation, a characteristic of GSCs, of GBM cells in vitro." (PMID 35008473, 2021).
tumor (continued). "There are several pathways influenced by IL-17 signals, such as Janus kinase 2 (JAK2)/STAT3, that possess a crucial role in regulating a number of processes related to tumorigenesis, including cell cycle progression, apoptosis, and tumor cell metastasis." (PMID 34948424, 2021). "In vivo, Phosphatase and tensin homolog (PTEN)-null senescent cells secrete cytokines through the Jak2/Stat3 pathway; promote the infiltration of immunostimulatory CD8+ T cells, NK cells, and B cells; and decrease the tumor size and invasion capacity." (PMID 32028565, 2020). "Consistent with the in vitro results, immunohistological analysis revealed that AT-I downregulated the expression of HK2, p-JAK2 and p-STAT3 in tumor tissuses of the xenograft mice." (PMID 32273843, 2020). "Studies have shown that the mechanism of microvessel proliferation and basal membrane degradation in other diseases, such as cancers and strokes, involves the JAK2/STAT3, IL-6/JAK2/STAT3, and MMP-9 pathways, which regulate the progression of tumor metastasis." (PMID 32047820, 2020). "One of the mechanisms for tumor cell-stimulated expression of PD-L1 is the activation of the EGFR, ERK1/2, PI3K-Akt, or Janus kinase 2/STAT1 signaling pathways." (PMID 32756527, 2020). "BMAs secrete a large amount of IL-6, which induces EMT in cancer cells through the JAK2/STAT3 pathway and increases the metastatic potential of tumor cells by promoting tumor cell survival through the PI3K/AKT pathway." (PMID 32674405, 2020). "Overall, these findings suggest that WDFY3‐AS2 is tumour suppressor lncRNA that inhibits cell proliferation and invasion by WDFY3‐AS2/miR‐2355‐5p/SOCS2/JAK2/Stat5 signalling pathway in ESCC cells." (PMID 32536038, 2020). "The efficacy of IKBKE pharmacological antagonism in vivo was tested using the Phase III, dual IKBKE/JAK2 antagonist, CYT387, on CWR22Rv1 tumour xenograft growth." (PMID 32324216, 2020). "The western blotting results showed that protein levels of p-JAK2 and p-STAT3 decreased significantly in NaB group in both tumor (T) and normal peritumoral (N) tissues (p < 0.001)." (PMID 32518521, 2020). "During tumor progression, specific endogenous ligands activate downstream pathways including the Ras/Raf mitogen-activated protein kinase (MAPK), Jak2/Stat3, and PI3K/AKT pathway." (PMID 32685551, 2020). "In vivo, AT-I significantly inhibited tumour growth and reduced the expression of HK2, phosphorylated JAK2 and STAT3." (PMID 32273843, 2020). "Functional experiments showed that DCZ0858 had a tumor-suppressive effect on DLBCL cells, mainly through cell proliferation inhibition, apoptosis induction, and cell cycle arrest via the JAK2/STAT3-signaling pathway." (PMID 32296013, 2020). "In particular, IL‐6 is the primary mediator of inflammation, which is the key to trigger the JAK2/STAT3 pathway, and plays a crucial role in tumor cell proliferation and invasiveness." (PMID 32677756, 2020). "JAK2 expression (P = 0.009), serum CA19-9 levels (P = 0.006), and histological tumor differentiation (P = 0.014) were related to OS." (PMID 33029256, 2020). "Vaccination with JAK2-mutant- and CALR-mutant-derived peptides will probably induce tumor-specific immune responses that will be further enhanced by co-vaccination with anti-regulatory epitopes, such as PD-L1- and ARG1-derived epitopes." (PMID 32630667, 2020). "One study established a positive feedback signaling loop formed by TGF-β and IL-6/JAK2/STAT3 signaling pathways, which mediates interactions between MF and tumor cells." (PMID 33262947, 2020). "Therapeutic vaccination with arginase or PD-L1 therefore offers a novel way to directly affect immune inhibitory pathways, potentially altering tolerance to tumor antigens like mutant CALR and mutant JAK2." (PMID 32630667, 2020).